RRP12 (ribosomal RNA processing 12 homolog)
Description:
Participates in the nucleoplasmic stage of pre-40S ribosomal subunit assembly, functioning as a scaffold for assembly factors and preparing pre-40S particles for export from the nucleus to the cytoplasm.
Synonyms: KIAA0690; IBGC11
Tractability: Small molecule: a structure with a bound ligand is known. Antibody: its Gene Ontology location is reachable by antibodies, with high confidence; UniProt predicts a signal peptide or a membrane-spanning region; the Human Protein Atlas places it where antibodies can reach. PROTAC: UniProt records ubiquitination sites on it; ubiquitination databases record sites on it; its protein half-life has been measured.
Gene: Protein-coding gene on chromosome 10 (97,356,357 to 97,426,076, reverse strand). Ensembl gene ENSG00000052749.
Subcellular location: Nucleus, nucleolus; Nucleus membrane
Subcellular location (Human Protein Atlas): Nucleoli; Cytosol; Plasma membrane; Vesicles
Gene Ontology:
Molecular function: RNA binding
Cellular component: nucleolus; plasma membrane; nuclear membrane
Genetic constraint (gnomAD): Loss-of-function variants: 65 observed, 142.52 expected, observed/expected ratio (o/e) 0.46, 90% interval 0.37 to 0.56. The upper end of that interval is the gene's LOEUF score, 0.56, which puts it in group 2 of 6, group 1 being the genes least tolerant of losing a copy. Missense variants: 1,470 observed, 1,653.4 expected, observed/expected ratio (o/e) 0.89, 90% interval 0.85 to 0.93. Synonymous variants: 705 observed, 668.41 expected, observed/expected ratio (o/e) 1.05, 90% interval 0.99 to 1.12.
Homologues: Orthologues: macaque RRP12 (98% identical), chimpanzee RRP12 (95% identical), rabbit RRP12 (92% identical), mouse Rrp12 (90% identical), rat Rrp12 (90% identical), guinea pig RRP12 (90% identical), dog RRP12 (88% identical), pig RRP12 (86% identical), tropical clawed frog rrp12 (68% identical), zebrafish rrp12 (61% identical), Drosophila melanogaster CG2691 (32% identical), Caenorhabditis elegans Y46E12BL.2 (28% identical).
Diseases named in the same sentence as RRP12 in open-access papers:
RRP12 is named in the same sentence as 19 diseases in open-access papers, as found by Europe PMC text mining. Sharing a sentence is not in itself a finding about the gene and the disease. The quoted sentences say what the papers report.
osteosarcoma (5 papers, 2020 to 2022). A usually aggressive malignant bone-forming mesenchymal neoplasm, predominantly affecting adolescents and young adults.
acute myeloid leukemia (1 paper, 2022). Acute myeloid leukemia (AML) is a group of neoplasms arising from precursor cells committed to the myeloid cell-line differentiation. "The results showed that RRP12 was only significantly upregulated in LAML (acute myeloid leukemia) while not statistically significant in the others (p>0.05)." (PMID 35178347, 2022).
adenoma (1 paper, 2021). A neoplasm arising from the epithelium. "Therefore, we explored the influence of RRP12 or SERPINH1 on the viability of adenoma cells at the organoid level." (PMID 34194496, 2021). "We then used this approach to achieve knockdown of RRP12 and SERPINH1 in adenoma organoids established from fresh surgical specimens; the effectiveness of the knockdown process was confirmed by ddPCR." (PMID 34194496, 2021). "Furthermore, RRP12 and SERPINH1 knockdown impeded the viability and proliferation of adenoma organoids." (PMID 34194496, 2021).
breast carcinoma (1 paper, 2021). "It has been reported that RRP12 is regulated by hsa-miR-140-3p and hsa-miR-200c in basal II breast cancer and may play an important role of tumor differentiation." (PMID 34194496, 2021).
chromophobe cell carcinoma of the kidney (1 paper, 2022). "However, in GBM (pleomorphic glioblastoma) and KICH (chromophobe cell carcinoma of the kidney), RRP12 was significantly down-regulated in both tumors compared with their corresponding normal samples." (PMID 35178347, 2022).
clear cell carcinoma of the kidney (1 paper, 2022). "For overall survival (OS), the results showed that the high expression of RRP12 is negative correlation with KIRC (clear cell carcinoma of the kidney) and LIHC (hepatocellular carcinoma) and the correlation had a poor prognosis (P<0.05), and the rest were not statistically significant." (PMID 35178347, 2022).
colon cancer (1 paper, 2021). "Among these RNMC-specific upregulated proteins, RRP12-like protein (RRP12), was positively correlated with poor prognosis of patients with colon cancer." (PMID 34590603, 2021).
colorectal cancer (1 paper, 2022). A primary or metastatic malignant neoplasm that affects the colon or rectum. "Recent researches have found that RRP12 is more highly expressed in colorectal cancer cells than in normal cells, and RRP12 can be used as a biomarker for the prognosis of colorectal cancer." (PMID 35178347, 2022).
hepatocellular carcinoma (1 paper, 2022). A malignant tumor that arises from hepatocytes. "Herein, we aimed to explore the role and significance of RRP12 in hepatocellular carcinoma.We used the TIMER and GEPIA databases to perform pan-cancer analyses of RRP12." (PMID 35178347, 2022). "Then, the effects of RRP12 on the proliferation, invasion, and metastasis of hepatocellular carcinoma cells were explored." (PMID 35178347, 2022). "Univariate and multivariate analysis showed that RRP12 could be used as an independent prognostic factor for patients with hepatocellular carcinoma." (PMID 35178347, 2022). "Hence, RRP12 can become a potential target and prognostic biomarker for the treatment of hepatocellular carcinoma." (PMID 35178347, 2022). "For disease-free survival (RFS), the results showed that only the high expression of RRP12 in LIHC (hepatocellular carcinoma) had a poor prognosis (p<0.05), and the rest were not statistically significant." (PMID 35178347, 2022). "However, there is no research on RRP12 in hepatocellular carcinoma." (PMID 35178347, 2022).
liver cancer (1 paper, 2022). An epithelial or non-epithelial malignant neoplasm that arises from the liver. "Scratch test, Transwell test, and Edu tests were applied to validate the effects of RRP12 on the function of liver cancer cells." (PMID 35178347, 2022). "Cellular experiments have proved that knocking down RRP12 can inhibit the proliferation, invasion, and metastasis of liver cancer cells.Therefore, RRP12 significantly affects the occurrence and development of HCC." (PMID 35178347, 2022). "So we concluded that the co-expressed genes of RRP12 in liver cancer were mainly related to rRNA processing and metabolic pathways." (PMID 35178347, 2022). "Through bioinformatics analysis, whether RRP12 is related to immune cell infiltration in liver cancer was investigated." (PMID 35178347, 2022). "Moreover, the expression of RRP12 in various liver cancer cells was evaluated by Western Blot to determine the cell line for the next experiment." (PMID 35178347, 2022). "Moreover, the prognostic analysis revealed that the difference in the expression of RRP12 has statistical significance for the overall survival rate and disease-free survival rate of liver cancer patients." (PMID 35178347, 2022). "Therefore, we speculate that RRP12 may affect the occurrence and development of liver cancer through immune cells." (PMID 35178347, 2022).
non-small cell lung carcinoma (1 paper, 2021). A group of at least three distinct histological types of lung cancer, including non-small cell squamous cell carcinoma, adenocarcinoma, and large cell carcinoma. "POLR1B regulates RRP12 to promote proliferation of non-small-cell lung cancer." (PMID 34194496, 2021).
rubella (1 paper, 2023). A viral infection caused by the rubella virus. "In rubella, including five in whole blood (JAGN1, RRP12, RP11-452K12.7, CASP7, and AP3S2), four in the lung tissue (IL17RC, FAM86HP, AMACR, and RRP12), and four in the transformed fibroblast cells (PPP2R1B, C11orf1, DLAT, and TMEM117)." (PMID 37020999, 2023).
sleeping sickness (1 paper, 2023). "HBA1, UBE2I, CSNK2A1, RRP12, and HSP90AB1 were highly enriched in African trypanosmiasis (sleeping sickness) than in the dengue viral infection pathway." (PMID 37498862, 2023).
cancer (4 papers, 2017 to 2022). A tumor composed of atypical neoplastic, often pleomorphic cells that invade other tissues. "In this study, through the expression and survival analysis of various human cancers, the differences in the expression and survival of RRP12 in HCC were identified." (PMID 35178347, 2022). "First, we conducted a pan-cancer analysis of RRP12 through the TIMER database and supplemented the research with the GEPIA database." (PMID 35178347, 2022). "This indicates that RRP12 may play an essential role in the occurrence and development of these 20 cancers." (PMID 35178347, 2022). "In the end, CCT6A, UTP18, YRDC, RRP12, RFT1, NLE1, and DDOST were essential genes across pan-cancer including COAD cells." (PMID 31867042, 2019). "Dependency score analysis by DepMap showed that ACTG1 and RHOQ were less essential across pan-cancer cells including COAD cell lines, and CCT6A, UTP18, YRDC, RRP12, RFT1, NLE1, as well as DDOST were essential across pan-cancer cells including most of COAD cell lines." (PMID 31867042, 2019). "In addition, CCT6A, UTP18, YRDC, RRP12, RFT1, NLE1, as well as DDOST were essential genes across pan-cancer including COAD cells, and ACTG1 and RHOQ were less essential genes in cancer cells." (PMID 31867042, 2019).
tumor (3 papers, 2021 to 2023). "Earlier, we found that the high expression of RRP12 was significantly positively correlated with tumor grade, stage, and T stage of HCC patients." (PMID 35178347, 2022). "The results showed that RRP12 was significantly high in tumor samples, consistent with the results from the Unanimous TIMER database." (PMID 35178347, 2022). "First, we used the R “beeswarm” package to study whether the expression of RRP12 was different in tumor samples and normal or adjacent samples." (PMID 35178347, 2022). "Moreover, it was speculated that RRP12 might be related to tumor proliferation, invasion, and metastasis." (PMID 35178347, 2022). "In order to analyze the correlation between the expression level of RRP12 and clinical parameters, it was found that there was a significant negative correlation with tumor stage, tumor grade and tumor size." (PMID 35178347, 2022).
RRP12 also shares sentences with these, for which no sentence is quoted: calcification (1 paper); generalized dystonia (1); glioblastoma (1); Onset (1).